COL3A1 (collagen type III alpha 1 chain)
Diseases named in the same sentence as COL3A1 in open-access papers (continued):
Sharing a sentence is not in itself a finding about the gene and the disease.
cancer (continued). "COL3A1 and COL5A1 are functionally related in connective tissue disorders, and expression of different collagens are associated with various cancers." (PMID 23383328, 2013). "Research has highlighted the role of COL3A1 in various cancer types." (PMID 38913913, 2024). "The 8 cell types were annotated based on the differentially expressed markers: Bnip3 for autophagic cancer cells, Mki67 for proliferating cancer cells, Cd14, Apoe, C1qc, Mrc1, Lyz2 for monocytes, Col3a1 for fibroblasts, Cd3e and Gzma for T cells, Flt1 for endothelial cells, and Klk1 for DCs." (PMID 38802348, 2024). "At the same time, multiple collagen-related genes (COL6A2, COL3A1, COL4A1, and COL4A2) in the MSC-2 cluster were upregulated in bone metastases, which is consistent with our observation of IGFBP3, TAGLN, LUM, COL6A1, COL6A2, and COL3A1 in pan-cancer in Fig. (1d)." (PMID 39156727, 2024). "Finally, a strong correlation was discovered between EMP1/COL3A1 genes and EMT-featured gene pan-cancer-wide, implying a possible underlying mechanism through an EMT perspective." (PMID 38187400, 2023). "Interestingly, through Pearson analysis, we also find a significant correlation between EMP1 and COL3A1 expressions in fibroblasts/osteoblasts among three types of cancer, suggesting a potential connection between these two genes." (PMID 38187400, 2023). "COL3A1 may serve as a molecular biomarker for assessing prognosis and immune infiltration in pan-cancer." (PMID 36860337, 2023). "On this basis, it can be hypothesized that RNF185, in a COL3A1-dependent manner, may act as a tumor suppressor in a broad spectrum of cancers; consequently, it may be targeted for the development of therapeutic strategies for different tumors." (PMID 38139010, 2023). "Studies reported up-regulated levels of COL3A1 by cancer progression." (PMID 36415513, 2022). "As expected, we identified that the upregulation of three collagen genes (COL1A1, COL3A1, and COL1A2), BTG2, and JUNB might be responsible for the radiation-associated secondary cancers in patients with BCa." (PMID 35274048, 2022). "The gene expression for COl1A1 in the cancer area was higher than Col3A1." (PMID 34771715, 2021). "Col1A1 collagen demonstrates most of the fibres in cancer tissue compared to Col3A1 collagen." (PMID 34771715, 2021). "We then checked the expression of the canonical cell-type markers: cancer/epithelial cell marker genes (Cdh1, Krt18, and Krt5); mesenchymal cell marker genes (Col1a1, Col1a2, and Col3a1); immune cell marker genes (Ptprc, Cd68, and Csf1r); and endothelial cell marker genes (Pecam1, Emcn, and Cdh5)." (PMID 34497807, 2021). "COL3A1 promotes the metastasis and invasion of cancer cells." (PMID 29301256, 2018). "Interestingly, plasma COL3A1 was notably increased in older peoples in either healthy (p = 0.016) or cancer individuals (p = 0.046)." (PMID 26741506, 2016). "COL3A1 has found to be increased in the stroma of other type of cancers." (PMID 26741506, 2016). "COL3A1 knockdown notably reduced cancer cell proliferation 2 days post-inoculation." (PMID 26741506, 2016). "Previous studies of cancer have demonstrated the role that COL3A1 can play in the proliferation of cancer cells, Furthermore, the overexpression of COL3A1 can lead to a significant decrease in the phosphorylation of the AKT/mTOR pathway, a pathway that is important for lactation." (PMID 33101361, 2020). "We discovered 22 hub genes influencing patient survival, among which COL3A1, PLAU, and SPP1 stood out for their overexpression in cancer compared to normal tissues." (PMID 41465316, 2025).
cancer (continued). "Previous studies have also reported dysregulation of COL1A1, COL1A2, COL3A1, and FN1 promoter methylation in various cancers." (PMID 38913913, 2024). "Our study demonstrated that COL3A1 exhibited the potency to become a prognostic biomarker for HNSCC, for it was more activated in cancer tissues than normal tissues, not only in the TCGA cohort but also in the practical patient cohort." (PMID 36039012, 2023). "Through L-R analysis, we identified COL3A1-ADGRG1 as a potential communication interaction between these fibroblasts and cancer cells." (PMID 38187400, 2023). "The “Target” run with ANGPTL3 as a target gene shows that altered genes of various cancer types including MAPK1, CASP5, COL3A1, ITGAM and TMEM59L change the expression of ANGPTL3." (PMID 37375208, 2023). "Among these proteins, the overexpression of MMP14, ITGA2, THBS2, COL1A1, COL3A1, COL11A1 and COL6A3 has been experimentally confirmed in PDAC, while that of COL12A1 and COL5A2 has been shown in other types of cancer." (PMID 34094925, 2021). "For example, COL3A1, a key gene in the constitution of the extracellular matrix (ECM), is significantly upregulated in the high-invasiveness score group in 26 cancer types." (PMID 33766047, 2021). "CAFs that overexpress COL3A1 and COL6A6 are presumed to be less effective in promoting cancer progression compared to those that show low overexpression." (PMID 33562096, 2021). "In conclusion, six core genes including COL3A1, EEF2, FN1, PTPRF SDC2, and RAC1, and several cancer-related metabolic processes, signaling pathways, and overall survival rate of patients were identified in BM PCa." (PMID 34229299, 2021). "It has been reported that COL3A1 can promote cell proliferation, migration, and monocyte recruitment in cancer, suggesting that the monocyte was recruited to the microenvironment of LSCC by COL3A1 while environment was stimulated by nicotine." (PMID 31217907, 2019). "All these findings indicated that the upregulation of COL3A1 and COMP is closely related to the occurrence and development of cancer." (PMID 29967488, 2018). "Among these genes, collagen 3A1 (COL3A1), collagen 4A1 (COL4A1), collagen 4A2 (COL4A2), and laminin 5 were upregulated in the majority of cancer lesions." (PMID 29720137, 2018). "We report that all of the studied collagen types (COL1A1, COL3A1, and COL6A1) in the AT, to be modulated by cancer cachexia." (PMID 28288584, 2017). "Another interesting pathways activated in both cancer cell lines is the extracellular matrix organization which involves up-regulation of different collagen genes like (COL1A1, COL1A2, COL3A1), and matrix metallopeptidase like (MMP8, MMP14)." (PMID 25077705, 2014). "The higher-than-normal tissue expression of COL3A1, DLG3, and RNF43 in some of the cancer tissues is in agreement with our in silico predictions." (PMID 23282184, 2012). "However, this is largely driven by high weightings of three collagen genes; COL1A1, COL3A1 and COL6A3, which steadily increase in inflamed, dysplasia and cancer samples compared to normal tissue samples, with adjusted P-values <0.003." (PMID 38505585, 2024). "Functional analysis indicated that the highly-expressed FAP in these cancers could affect extracellular matrix organization process and interacted with genes like COL1A1, COL1A2, COL3A1 and POSTN." (PMID 37325617, 2023). "The interaction between COL3A1 from fibroblasts and ADGRG1 from cancer cells might contribute to the BoM process and these findings are worth future validation through either in vitro or in vivo studies." (PMID 38187400, 2023). "Enriched EMP1+ fibroblasts were found in BoM samples, and a COL3A1-ADGRG1 communication between these fibroblasts and cancer cells was identified which might facilitate the BoM process." (PMID 38187400, 2023).
cancer (continued). "Therefore, our database-based pan-cancer analysis suggests that these four collagen family genes (COL5A1, COL3A1, COL4A1, and COL15A1) have commonality with the progression of various tumors." (PMID 34691289, 2021). "Immunohistochemistry analysis of a tissue microarray (n = 90) demonstrated that cancer epithelial but not stromal COL3A1 was significantly upregulated comparing with the normal counterparts." (PMID 26741506, 2016). "Interestingly, upon the real-time qPCR analysis of three cancer differentially expressed secreted protein gene candidates, COL3A1, DLG3, and RNF43 identified in this study, higher cancer expression levels of these genes in multiple cancer types were verified." (PMID 23282184, 2012). "Module III represents CAFs expressing COL1A1, COL1A2, and COL3A1 enriched in the cancer regions, whereas module IV identifies a subset known as myofibroblasts (myCAFs) (COL12A1, THBS2) that mainly contribute to extracellular matrix remodeling and growth and metastasis of cancer cells." (PMID 40033360, 2025). "Interestingly, with the exception of COL3A1, all the shared genes directly interact with each other, suggesting that they form the core of a GBM pathway, and that non-shared cancer genes are extensions of the core network." (PMID 20482850, 2010).
connective tissue disorder (31 papers, 2012 to 2025). A disease involving the connective tissue. "Inherited connective tissue disorders are also implicated, including vascular Ehlers–Danlos syndrome caused by COL3A1 mutations, Marfan syndrome due to FBN1 mutations, and Loeys–Dietz syndrome associated with mutations in genes of the TGF-β pathway." (PMID 41303555, 2025). "These investigations identified potentially pathogenic variants in genes linked to connective tissue disorders (COL3A1, COL1A2, and SMAD3), as well as variants of uncertain significance in other genes associated with SCAD and vascular fragility." (PMID 41303555, 2025). "Vascular Ehlers-Danlos syndrome (vEDS) is a rare inherited connective tissue disease caused by mutations in the COL3A1 gene." (PMID 41272811, 2025). "In 1988, the first connective tissue disorder definitively associated with arterial disease, including thoracic aortopathy, implicated mutations to COL3A1, the gene that encodes the individual alpha helices that constitute the collagen III molecule." (PMID 39830801, 2025). "Vascular Ehlers-Danlos syndrome (vEDS) is a rare inherited connective tissue disorder predominantly caused by pathogenic COL3A1 variants." (PMID 39730916, 2025). "Vascular Ehlers Danlos Syndrome (vEDS) (OMIM # 130050) is a rare heritable connective tissue disorder caused by heterozygous mutations in the gene COL3A1 that encodes the alpha 1 chain of collagen III, α1(III)." (PMID 40280907, 2025). "Vascular Ehlers-Danlos Syndrome (vEDS) is a rare connective tissue disorder associated with COL3A1 gene mutation encoding type III collagen." (PMID 37936948, 2023). "Vascular Ehlers‐Danlos syndrome (vEDS) is a rare and severe hereditary connective tissue disease arising from a mutation in the type III collagen alpha I chain (COL3A1) gene, with a poor prognosis due to exceptional vascular ruptures and premature death." (PMID 34845833, 2022). "Although no phenotypic features of connective tissue diseases were evident, genetic screening of the 28 vascular dissection and aneurysm-associated genes (a connective tissue disease panel) identified a variant in COL3A1 (c.3199A > T, Ser1067Cys)." (PMID 36561772, 2022). "Two of her adult daughters showed the same COL3A1 gene variant and features of a connective tissue disorder including hyperflexibility and joint pain." (PMID 35205368, 2022). "In contrast to these direct connective tissue disorders (COL3A1 and FBN1 mutations), well over a decade later it was discovered (in 2005) that mutations to genes (TGFBR1, TGFBR2) that encode receptors of the transforming growth factor-β (TGF-β) system also predispose to thoracic aortopathies." (PMID 39830801, 2025). "Vascular Ehlers–Danlos syndrome or Ehlers–Danlos syndrome type IV (vEDS) is a connective tissue disorder characterised by skin hyperextensibility, joint hypermobility and fatal vascular rupture caused by COL3A1 mutations that affect collagen III expression, homo-trimer assembly and secretion." (PMID 39201504, 2024). "In addition, atypical variants of COL3A1 were associated with Ehlers–Danlos syndrome (EDS) involving connective tissue disorders." (PMID 36776313, 2023). "vEDS syndrome is a rare connective tissue disorder caused by a COL3A1 mutation." (PMID 34239643, 2021). "Col1a1 and Col3a1 are used as markers for valvular integrity, cardiac fibrosis, and connective tissue disease." (PMID 33322681, 2020). "For this reason, the same revised Ghent nosology recommends supplementing genetic tests with analyses of TGFBR1, TGFBR2, COL3A1, and collagen biochemistry, especially when symptoms of MFS overlap with those of other connective tissue disorders." (PMID 37688493, 2024).
infection (14 papers, 2014 to 2026). The state of being infected such as from the introduction of a foreign agent such as serum, vaccine, antigenic substance or organism. "The increase in VH was likely supported by increases in Col3a1 and Notch1 mRNA on 7 and 10 dpi; while the crypt elongation was reinforced by increased Ki67 mRNA following infection." (PMID 36867919, 2023). "One of the downregulated genes in the trophoblasts from CZS-affected twins after ZIKVBR infection was COL3A1." (PMID 32745093, 2020). "Robust changes in expression of several genes was evident 7 days post-infection; expression of Col1a1, Col1a2, Col3a1, Mmp2, Mmp9 and Lox was significantly increased while expression of Timp3 was significantly decreased." (PMID 24950301, 2014). "The contribution of stellate cells—whose markers of the activated form are Acta2, Col1a1, Tagln, Col1a2, Col3a1, Sparc, and Rbp1—changed significantly only during infection with C. sinensis compared to the control (pairwise Kruskal–Wallis test with Benjamini–Hochberg correction, Padj = 0.030)." (PMID 39652576, 2024). "In the later stage of infection, focal adhesion pathway was associated with ECM receptor interaction pathway through SPP1, col6a2, COL3A1 and VTN proteins, while focal adhesion pathway linked with leukocyte transendothelial migration pathway by RAC1 and LOC733637." (PMID 32632500, 2020). "Cell-to-cell communication analysis further indicated that the interaction between the epithelial, vascular endothelial, pDCs, and fibroblast subsets, except for COL3A1 fibroblasts, was enhanced mainly via CD74/(COPA or MIF) receptor ligands after infection." (PMID 41843736, 2026). "Also, whereas collagen proteins were downregulated during infection of HFFF-TERTs, the same proteins were upregulated in THP-1s (COL1A1, COL1A2, COL3A1, COL5A1, and COL12A1)." (PMID 38065956, 2023).
heart diseases (2 papers, 2015 to 2020). "Through big data analysis, we found that HBP family members, such as HP, CXCL12, COL3A1, PECAM1, and other highly correlated genes, play a role in heart diseases." (PMID 32612856, 2020).
cardiovascular disease (1 paper, 2020). "Furthermore, the key genes identified by MCODE analysis, HP, CXCL12, COL3A1, and PECAM1, may also serve as candidate targets for cardiovascular disease diagnosis." (PMID 32612856, 2020).
CNS tumors (1 paper, 2025). "Additionally, these previous studies did not classify patients based on the latest WHO classification of CNS tumors, which could further influence the interpretation of the prognostic role of CD163 and COL3A1." (PMID 40427760, 2025).
respiratory disease (1 paper, 2014). "Therefore, while COL3A1 expression generally decreases with aging over time to possibly reduce age-related tissue remodeling, smoking-induced expression may contribute significantly to the increased incidence of airway remodeling in individuals with smoking-induced respiratory disease such as COPD." (PMID 25248511, 2014).
COL3A1 also shares sentences with these, for which no sentence is quoted: hypertrophy (4 papers); vascular disorder (4); diabetic nephropathy (3); glaucoma (3); sarcopenia (3); dissection (2); familial hypercholesterolemia (2); genetic disease (2); head and neck cancer (2); idiopathic pulmonary fibrosis (2); intracranial aneurysms (2); lipoblastoma (2); malignant glioma (2); metabolic syndrome (2); myopathy (2); neurodegenerative disease (2); osteogenesis imperfecta (2); rheumatoid arthritis (2); viral infection (2); William Beuren syndrome (2); abdominal aortic aneurysm (1); adenocarcinoma (1); adenomyosis (1); alcoholic liver diseases (1); Andersen syndrome (1); Aortic Rupture (1); aortic stenosis (1); arrhythmogenic right ventricular cardiomyopathy (1); autosomal dominant inherited disorder (1); autosomal dominant polycystic kidney disease (1).
A further 96 diseases each share a sentence with COL3A1 in 1 paper.